MMP9 (matrix metallopeptidase 9)
Diseases named in the same sentence as MMP9 in open-access papers (continued):
Sharing a sentence is not in itself a finding about the gene and the disease.
Alzheimer disease (continued). "We found little evidence to suggest that CypA or MMP9 affects the risk of Alzheimer’s disease or cognitive impairment using two-sample Mendelian randomization and polygenic risk score analysis in humans." (PMID 35058547, 2022). "We used linear mixed effects models to examine whether sex modified total and free plasma MMP-9 associations with cognition, using longitudinal Mini-Mental Status Examination (MMSE) and Alzheimer’s Disease Assessment Scale-Cognitive Subscale (ADAS-cog) data." (PMID 36324151, 2022). "Neuromorphologists soon unveiled that MMP-9 is also involved in perineuronal net maintenance, and that elevated MMP-9 levels may contribute to both perineuronal net degradation and altered levels of β-amyloid in Alzheimer’s disease." (PMID 36232390, 2022). "Interestingly, increased levels of cyclophilin A and MMP-9 in endothelial cells and pericytes of cerebral microvessels were found in patients with Alzheimer’s disease who carry the APOE4 gene; those correlated with BBB breakdown." (PMID 34796023, 2021). "In individuals with the APOE4 allele, who are at high risk for Alzheimer’s disease, secreted APOE4 activates the release of matrix metalloproteinase-9 (MMP9) in pericytes, disrupting the junctions between endothelial cells and increasing the influx of Aβ into the brain (Ishii and Iadecola, 2020)." (PMID 34497540, 2021). "Twelve different proteins significantly altered by 48 hr after mTBI mapped to 11 different functional pathways, pathological pathways were: Apoptosis signaling pathway (P00006, FASL, TNF-R2), FAS signaling pathway (P00020, FASL) and Alzheimer disease-presenilin pathway (P00004, E-Cadherin, MMP-9)." (PMID 32804078, 2020). "An increase in MMP9, perhaps due to the increased NO levels seen in Alzheimer’s disease, may then give rise to an increase in the degradation of NGF." (PMID 22654716, 2011). "Our findings highlight the contribution of neural/glial MMP-9 to Aβ-induced neurotoxicity and cognitive impairment and support the idea that for highly selective MMP-9, inhibitors may reduce deleterious proteolytic activity and neuronal death in Alzheimer's disease." (PMID 22235372, 2011). "Interestingly, MMP-9 levels are increased in the brains of patients with Alzheimer's disease." (PMID 22235372, 2011). "This study investigated the diagnostic accuracy of plasma biomarkers—specifically, matrix metalloproteinase (MMP-9), tissue inhibitor of metalloproteinase (TIMP-1), CD147, and the MMP-/TIMP-1 ratio in patients with Alzheimer’s disease (AD) dementia." (PMID 38891891, 2024). "SOD1 has not been reported in AAA, but when treated with hydroxyl ethanol, it inhibits Ang II-induced Alzheimer’s disease, decreases the expressing of NF-κB, P65, TNF-α, and IL-1β, and increases the conveying of SOD1, MMP9, and GCLC in mice." (PMID 37737183, 2023). "In human tissue, MMP-9 expression increased already in moderate-stage Alzheimer’s disease, whereas MMP-2 expression increased only in late-stage Alzheimer’s disease." (PMID 36232390, 2022). "Studies have reported higher plasma matrix metalloproteinase-9 (MMP-9) levels in mild cognitive impairment (MCI) and Alzheimer’s disease (AD)." (PMID 36324151, 2022). "Matrix metalloprotein-9 (MMP-9) and tight junction protein Claudin-5 have been shown to regulate BBB permeability and play an important role in neuropathologies such as Alzheimer’s disease." (PMID 32326620, 2020). "In the transgenic 5X FAD mouse model of Alzheimer's disease (AD) the expression of MMP-2, MMP-9, and MT1-MMP was upregulated concomitantly with the tissue inhibitor of MMPs-1 (TIMP-1) and several markers of inflammatory/glial response." (PMID 26733793, 2015). "MMPs and TIMPs have been also investigated as potential markers for dementia, resulting with the identification of altered plasma levels of MMP-9 and TIMP-1 in Alzheimer's Disease and vascular dementia, respectively." (PMID 20161799, 2010).
Alzheimer disease (continued). "Additional targets such as APP (amyloid precursor protein) implicate potential connections to Alzheimer’s disease pathology, while MMP9 (matrix metalloproteinase-9) may modulate extracellular matrix remodeling and blood–brain barrier integrity." (PMID 40943635, 2025). "Finally, we were interested in learning how the elevated levels of active MMP-9 observed in the serum of ALS compared with other inflammatory diseases, such as diabetic nephropathy, Alzheimer’s disease, and Parkinson’s disease." (PMID 41009467, 2025). "MMP‐9 is associated with ECM remodeling and discriminates well between patients with vascular cognitive impairment and Alzheimer's disease, but it is possible that measurement in the serum is not sensitive enough to capture a treatment effect." (PMID 38629936, 2024). "When investigating plasma samples, a decrease of MMP-2 and MMP-10, but no change in MMP-9 expression level, was reported in Alzheimer’s disease patients." (PMID 36232390, 2022). "There was little evidence that CypA or MMP9 eQTLs or pQTLs affected the odds of Alzheimer’s disease, and these estimates were very precise." (PMID 35058547, 2022). "In the rat Alzheimer’s disease model, resveratrol defends BBB integrity by reducing advanced glycation end products (RAGE), matrix metalloprotein-9 (MMP-9) and increasing Claudin-5 but also reduces neuroinflammation by affecting nuclear factor NF-κB expression." (PMID 32326620, 2020). "Interestingly, MMPs have been characterized as bifunctional proteins in Alzheimer's disease, with some of them, such as MMP-2 and MMP-9, displaying protective roles during disease progression, while others promote disease evolution." (PMID 32454796, 2020). "PANTHER pathways analysis of differentially expressed proteins revealed overrepresentation of Wnt signaling pathway (CDH1, CSNK2A2, GNA11, CTBP2, CDH17, SMARCE1, p-value 0.02), followed by Alzheimer disease-presenilin pathway (MMP8, MMP9, MLLT4, CDH1, P-value 0.04)." (PMID 29515771, 2018). "Matrix metalloproteinase-9 (MMP-9), a major component of the basement membrane, may contribute to the pathogenesis of neurodegenerative diseases such as Alzheimer’s disease, PD and ALS by inducing neuronal death –." (PMID 24040066, 2013). "Genome-wide association study meta-analysis conducted mainly on participants of European origin showed a little evidence that MMP-9 expression quantitative trait loci (eQTLs) and protein quantitative trait loci (pQTLs) affected the odds of Alzheimer’s disease (p = 0.45 and p = 0.51)." (PMID 37206663, 2023). "Matrix metalloproteinase-9 (MMP-9) is a zinc-dependent enzyme, that belongs to the family of MMPs and contributes to the neuroinflammatory response in neuroinflammation and in neurodegenerative diseases such as amyotrophic lateral sclerosis, and Alzheimer's disease." (PMID 22018032, 2011). "CSF concentrations of MMP-9 decrease, concentrations of MMP-3 increase, whilst neither MMP-2 nor TIMPs show significant changes in Alzheimer’s disease patients." (PMID 36232390, 2022). "A second study found that 79% of CAA-affected vessels were immunopositive for MMP-9 in CAA cases with (n = 4) and without (n = 6) Alzheimer disease (AD), while only 5% of control vessels were immunopositive for MMP-9 (n = 4 non-CAA control cases)." (PMID 30483207, 2018).
Cognitive impairment (73 papers, 2010 to 2025). Abnormal cognition is characterized by deficits in thinking, reasoning, or remembering. "Higher MMP-9 levels have also been linked to a higher risk of cognitive impairments, according to clinical results." (PMID 39997037, 2025). "A rise in blood levels in regard to MMP-9 is correlated with a number of cognitive impairments linked to diseases such psychoses, schizophrenia, and epilepsy." (PMID 39997037, 2025). "Our study warrants further investigations into the treatment potential of MMP-9 modulators and inhibitors in alleviating cognitive deficits that are associated with many psychiatric disorders but are currently untreatable." (PMID 38431757, 2024). "Clinical findings demonstrated an association between higher MMP-9 levels and an increased risk for cognitive impairments." (PMID 38431757, 2024). "On the other hand, the injection of Aβ increases MMP9 expression, and this increase has been associated with the development of cognitive impairment and neurotoxicity." (PMID 38883967, 2024). "TNF-α and MMP-9 are pro-inflammatory cytokines and proteases, respectively, which have been implicated in the pathophysiology of cognitive impairment." (PMID 39135795, 2024). "Because MMP inhibitors alleviate cognitive impairment in vivo as well as neurotoxicity in vitro, MMP-9 likely plays a causal role in β-amyloid-induced cognitive impairment and neurotoxicity." (PMID 36232390, 2022). "Another study showed that CyPA and MMP9 levels in serum were associated with cognitive impairment and white matter signal abnormalities, which is controversial in our study." (PMID 36003963, 2022). "Abnormal levels of metalloproteinases, including MMP-9, in plasma have been associated with AD progression and increased permeability of the blood-brain barrier, a driver of cognitive impairment." (PMID 36438010, 2022). "A clinical study showed that the increased serum MMP9 level in acute phase of IS was associated with 3-months cognitive impairment." (PMID 34992531, 2021). "In fact, treatment with GM6001, an MMP inhibitor, ameliorated Aβ-induced impairment of recognition memory, suggesting that transient increases in hippocampal MMP-9 activity are associated with the development of Aβ-induced cognitive deficits." (PMID 22235372, 2011). "Interestingly, higher plasma MMP-9 concentration has been shown to be associated with a greater risk of AD development in APOE ε4 carriers with mild cognitive impairment." (PMID 41009358, 2025). "Furthermore, clinical findings demonstrated an association between higher MMP-9 levels and an increased risk for cognitive impairments in psychosis." (PMID 38431757, 2024). "Therefore, we suggest that the occurrence of cognitive impairment in PD patients is associated with elevated levels of MMP9." (PMID 36072482, 2022). "Therefore, future studies examining the influence of APOE ε4 on sex differences in MMP-9 associations with AD pathology and cognitive impairment are warranted." (PMID 36324151, 2022). "Indeed, LRP1 downregulation doesn’t only affect Aβ clearance but causes as well BBB breakdown through activation of MMP-9, thus leading to loss of neurons and cognitive deficits." (PMID 34566627, 2021). "In addition, we also examined the joint effect of serum TIMP‐1 and MMP‐9 on the risk of subsequent cognitive impairment." (PMID 32431079, 2020). "Increased TIMP‐1 and MMP‐9 levels may disrupt the microvascular basal layer and lead to leukoaraiosis, which in turn causes cognitive impairment and dementia." (PMID 32431079, 2020). "Similarly, by using iTRAQ-based proteomics, protein S100-A9 and metalloproteinase-9 (MMP9) are found to be associated with inflammation and cognitive impairment induced by HIV." (PMID 28391008, 2017).
Cognitive impairment (continued). "As improper maturation of sensory networks during development is implicated in many neurodevelopmental disorders and in cognitive deficits, understanding the mechanisms of MMP-9 mediated synaptic plasticity is essential for the development of therapeutic strategies." (PMID 26283917, 2015). "We suggest, although with extreme caution, that the decrease of MMP-9 levels observed in our clusters might be interpreted in analogy with data on Fragile X syndrome (FXS), a condition associated with cognitive deficits, anxiety, mood imbalance, and increased MMP-9 plasma levels." (PMID 37004521, 2023). "Therefore, prophylactic procyanidin administration rescues the cognitive impairment caused by cisplatin, which may be achieved by inhibiting MMP-9 expression and BBB damage." (PMID 35624958, 2022). "Moreover, MMP9 has been found to play a causal role in amyloid β (Aβ)-induced cognitive impairment and neurotoxicity, as intracerebroventricular injection of Aβ induced cognitive deficits and MMP9 expression in the mouse hippocampus, while Aβ exposure caused neurotoxicity in cultured neurons." (PMID 34034683, 2021). "Additionally, both MMP9 and apoE4 have been implicated in early AD pathology before the onset of cognitive impairment, so therapeutic approaches targeting MMP9 may require early administration to see the greatest benefits." (PMID 34034683, 2021). "Meanwhile, MMP9 derived peripheral neutrophils contribute to postoperative cognitive impairment in aged mice by increasing the permeability of the blood-brain barrier." (PMID 40918113, 2025). "Its administration enhanced catalase activity and GSH levels while reducing hippocampal NF-κB and MMP-9 expression, highlighting the complex interplay between oxidative stress, inflammation, and cognitive impairment." (PMID 41155598, 2025). "Conversely, microglia depletion or the inhibition of MMP9 activity can reverse the cognitive impairment induced by glial activation." (PMID 40918113, 2025). "MMP9 is a potential AD biomarker for disease progression, with higher serum levels of MMP9 correlated with faster cognitive decline in patients with mild cognitive impairment attributed to AD." (PMID 40078479, 2025). "This study improves our understanding of the roles of MMP9, which serve as a mediator for microglial polarization, leading to exacerbated neuroinflammation and subsequent cognitive impairment." (PMID 40918113, 2025). "In fact, reliable biomarkers that can predict immediate surgical outcomes and long-term neurological and cognitive deficits are needed, reinforcing the potential relevance of MMP-9 in this context." (PMID 40364266, 2025). "In dementia, blood MMP-9 upregulation was a driver of blood-brain barrier breakdown and cognitive impairments." (PMID 38431757, 2024). "The level of MMP-9 in CSF has been associated with NPSLE in general, and especially cognitive impairment." (PMID 37684700, 2023). "A study on the Tg-APP/PS1 mouse AD model reported that hyperoxygenation increases the production of MMP-2, MMP-9, and tPA, leading to reduction of Aβ deposition in the brain and rescued cognitive impairment." (PMID 37109410, 2023). "An elevation of MMP9 has been reported to accompany BBB leakage and vasogenic edema following ischemic stroke, which leads to cognitive impairment." (PMID 36531742, 2022). "Procyanidin (20, 40 mg/kg, p.o.)suppressed cisplatin-related MMP-9 level increase, BBB interruptions, and cognitive impairment caused by cisplatin." (PMID 35624958, 2022). "Hyperoxygenation treatment upregulates MMP-2, MMP-9 and tPA expression which reduces β-amyloid accumulation and rescues cognitive impairment in APP/PS1 transgenic mice." (PMID 36232390, 2022). "Previous studies have shown that MMP9 activity in brain samples from patients with mild cognitive impairment is significantly higher than that in patients with normal cognitive function and that MMP9 activity is negatively correlated with the MMSE score." (PMID 36072482, 2022).
Cognitive impairment (continued). "Mizoguchi and colleagues demonstrated that inhibition of MMP9 reduced neurotoxicity in Aβ-treated cell cultures and reversed Aβ-induced cognitive impairment in vivo." (PMID 35454094, 2022). "The knockout of MMP-9 rescues cognitive impairment and cisplatin-induced upregulation of HMGB1 in SHSY5Y cells." (PMID 35624958, 2022). "We found significant differences in MMP9 levels between the cognitive impairment subgroups and cognitive integrity subgroups." (PMID 36072482, 2022). "The upregulation of MMP-9 has been suggested to be involved in several neurodegenerative disorders, since higher MMP-9 activity and concentration are related to cognitive impairment." (PMID 33808221, 2021). "MMP9 is associated with BBB permeability, and the inhibition of MMP9 reduces Aβ-induced cognitive impairment." (PMID 34829528, 2021). "In the current study, we examined the effect of simvastatin administration on hippocampal MMP-9 expression in an animal model of cognitive impairment induced by intracerebroventricular (ICV) streptozotocin (STZ) administration." (PMID 30218997, 2019). "In the present study, we evaluated the effect of oral simvastatin on hippocampal MMP-9 expression in a rat model of cognitive impairment induced by streptozotocin (STZ) infusion into the cerebral ventricles (ICV)." (PMID 30218997, 2019). "Oral administration of simvastatin, 5 mg/kg body weight for three weeks after STZ infusion, prevented the up-regulation of MMP-9 gene expression, reduced neuronal damage in hippocampal tissue and subsequently improved cognitive impairment." (PMID 30218997, 2019). "Our results are in agreement with a previous finding that demonstrated MMP-9 involvement in the pathogenesis of brain injuries and cognitive disorders." (PMID 30218997, 2019). "Our findings suggest that the neuroprotective influence of simvastatin in battle to cognitive impairment is mediated in part by the modulation of MMP-9 expression." (PMID 30218997, 2019). "The present results showed that hippocampal MMP-9 up-regulated in the rat model of cognitive impairment induced by intracerebro-ventricular injection of STZ." (PMID 30218997, 2019). "It has been shown that MMP-9 activity in the frontal and parietal cortex is greater in both AD and mild cognitive impairment compared to healthy subjects." (PMID 30218997, 2019). "Serum MMP-9 levels have been shown to be positively correlated with the severity of cognitive impairment." (PMID 26768000, 2016). "Strikingly, a correlation between cognitive impairment and MMP-9 activity was observed in patients with mild cognitive impairment." (PMID 26538832, 2015). "Serum levels of MMP-9 were also found elevated in AD compared to controls and patients suffering from mild cognitive impairment." (PMID 25050378, 2014). "These provide insight that MMP9 may play a role in the neuroinflammatory process that leads to cognitive impairment in PD, and Asp G may serve as a high-affinity ligand for MMP9." (PMID 40422771, 2025). "Moreover, the Aβ-induced cognitive impairment was significantly reduced by MMP-9 gene silencing or treatment with MMP inhibitors." (PMID 35330183, 2022). "In conclusion, our findings suggest that sex modulates the influence of MMP-9 on AD-related pathology and cognitive impairment and may crucially inform our understanding of the factors determining its role in AD pathological changes." (PMID 36324151, 2022). "High plasma MMP-9 levels increase the conversion risk between mild cognitive impairment (MCI) patients with and without ApoE4." (PMID 36232390, 2022). "Importantly, the Aβ-induced cognitive impairment in vivo as well as neurotoxicity in vitro was significantly alleviated in MMP-9 homozygous knockout (KO) mice and treatment with MMP inhibitors." (PMID 34034683, 2021).